LDOC1 (LDOC1 regulator of NFKB signaling)
Description:
May have an important role in the development and/or progression of some cancers.
Synonyms: BCUR1; Mar7; Mart7; SIRH7; RTL7
Tractability: No criterion of Open Targets' tractability assessment is met for any kind of drug.
Gene: Protein-coding gene on chromosome X (141,111,605 to 141,177,129, reverse strand). Ensembl gene ENSG00000182195.
Subcellular location: Nucleus
Subcellular location (Human Protein Atlas): Nucleoli; Nucleoplasm
Gene Ontology:
Molecular function: protein binding
Biological process: cellular response to lipopolysaccharide; cellular response to muramyl dipeptide; negative regulation of cell population proliferation
Cellular component: nucleolus; nucleoplasm; nucleus
Homologues: Orthologues: pig LDOC1 (97% identical), guinea pig LDOC1 (95% identical), macaque LDOC1 (80% identical), rat Ldoc1 (73% identical), mouse Ldoc1 (72% identical). Paralogues in human: RTL8B (45% identical), RTL8A (43% identical), RTL8C (42% identical), RTL5 (30% identical), RTL3 (28% identical), RTL6 (28% identical), RTL1 (25% identical), PEG10 (24% identical), RTL10 (21% identical), RTL4 (8% identical).
Diseases named in the same sentence as LDOC1 in open-access papers:
LDOC1 is named in the same sentence as 48 diseases in open-access papers, as found by Europe PMC text mining. Sharing a sentence is not in itself a finding about the gene and the disease. The quoted sentences say what the papers report.
cervical cancer (6 papers, 2015 to 2022). A primary or metastatic malignant neoplasm involving the cervix. "Hyper-methylation causes LDOC1 silencing in multiple tumor types, such as cervical cancer, lung cancer, and oral squamous cell carcinoma, implying the accuracy and efficacy of our prediction." (PMID 32528944, 2020). "The expression of LDOC1 is also decreased in several smoking-associated cancers including cervical cancer, esophageal adenocarcinoma, pancreatic ductal adenocarcinoma, and head and neck cancers." (PMID 26317789, 2015). "Promoter methylation and the loss of LDOC1 expression are frequent events in cervical cancer and could be potential molecular markers in cervical cancer." (PMID 29850477, 2018). "Previous studies have found that the LDOC1 expression is reduced in certain malignancies, including colorectal cancer, cervical cancer, pancreatic cancer, prostate cancer, and papillary thyroid carcinoma." (PMID 35957693, 2022). "The hypermethylation of the LDOC1 promoter region and the downregulation of LDOC1 in ovarian and cervical cancer cell lines increase cell proliferation." (PMID 30993049, 2019). "Another key finding was that overexpression of HAND2-AS1 inhibited proliferation, migration and invasion of cervical cancer cells through upregulating LDOC1 by binding to miR-330-5p." (PMID 31889905, 2019). "Low expression of HAND2-AS1 and LDOC1, and high expression of miR-330-5p were detected in cervical cancer tissues and cells." (PMID 31889905, 2019). "More interestingly, in agreement with our findings, another group found that LDOC1 was poorly expressed in cervical cancer, and overexpression of LDOC1 was able to induce cell apoptosis in cervical cancer cells." (PMID 31889905, 2019). "Our RT-qPCR experimental results also demonstrated a poor expression of LDOC1 in cervical cancer tissues." (PMID 31889905, 2019). "Taken together, these results confirm that HAND2-AS1 inhibits expression of LDOC1 by binding to miR-330-5p to affect the proliferation and metastasis of cervical cancer cells." (PMID 31889905, 2019). "HAND2-AS1 promotes LDOC1 expression by competitively binding to miR-330-5p and consequently inhibiting cervical cancer cell invasion and metastasis." (PMID 31889905, 2019). "As a next step to understand the interplay of HAND2-AS1, miR-330-5p and LDOC1 in cervical cancer, HeLa cells transfected with appropriate plasmids were used to investigate cell proliferation, invasion and metastatic ability of cells." (PMID 31889905, 2019). "The expression patterns of HAND2-AS1, microRNA-330-5p (miR-330-5p) and leucine zipper down-regulated in cancer 1 (LDOC1) in cervical cancer were characterized by RT-qPCR and western blot analysis." (PMID 31889905, 2019). "Thus the levels of LDOC1 in patient samples were analyzed using RT-qPCR and immunohistochemistry revealing the poor expression of LDOC1 in cervical cancer tissues in comparison to adjacent tissues (all p < 0.05)." (PMID 31889905, 2019). "Likewise, in the present study we observed that miR-330-5p inhibits the expression of LDOC1 and thus promotes proliferation, invasion and metastasis of cervical cancer cells." (PMID 31889905, 2019). "This study investigated the role of HAND2-AS1 in cervical cancer, which uncovered that HAND2-AS1 could promote LDOC1 expression by competitively binding to miR-330-5p, thus inhibiting invasion and metastasis of cervical cancer cells." (PMID 31889905, 2019).
lung carcinoma (6 papers, 2015 to 2024). "The downregulation of Leucine Zipper Down-Regulated In Cancer 1 (LDOC1) in cancer patients is associated with the low survival rate of lung cancer patients." (PMID 36591515, 2022). "Immunohistochemistry studies showed that LDOC1 downregulation is associated with poor survival of patients with lung cancer." (PMID 30634502, 2019). "Bhattacharjee's study showed that the LDOC1 expression was relatively low in small cell lung carcinoma—a lung cancer type strongly associated with smoking." (PMID 26317789, 2015). "Therefore, epigenetically silencing of LDOC1 by tobacco exposure promotes lung cancer progression and suggests that LDOC1 downregulation is a biomarker associated with poor survival of patients with lung cancer." (PMID 30634502, 2019). "Given the close association between cigarette smoke and lung cancers, we proposed that LDOC1 may play a role in the pathogenesis of lung cancers." (PMID 30634502, 2019). "Collectively, these data indicated that LDOC1 is a susceptible epigenetic target when human respiratory tracts are exposed to cigarette smoke and suggested that LDOC1 plays a possible role in the malignant progression of lung cancer." (PMID 30634502, 2019). "Therefore, it is possible that LDOC1 might decrease expression by cigarette exposure in lung of smokers and smoking-associated lung cancer." (PMID 26317789, 2015). "The down-regulation of miR-19b (0.397-fold change, p < 0.001) is potentially responsible for the up-regulation of LDOC1 in S. aureus-induced mastitis, which has been identified to be the candidate marker for lung cancer and diabetes." (PMID 33922375, 2021). "Overall, our results elucidated a crucial role of LDOC1 in lung cancer and revealed how LDOC1 acts as a bridge between tobacco exposure and the IL-6/JAK2/STAT3 loop in this human malignancy." (PMID 30634502, 2019). "Our preliminarily data indicated that LDOC1 knockdown yielded a drop in reactive oxygen species (ROS) in lung cancer cells." (PMID 30634502, 2019). "Weak or silenced LDOC1 expression was observed in 60.4% of the lung cancer tissues, whereas 39.5% of the lung cancer tissues exhibited LDOC1 immunostaining." (PMID 30634502, 2019). "In this study, we demonstrated the tumor suppressor function of LDOC1 in lung cancer." (PMID 30634502, 2019). "Because LDOC1 is a regulator of the IL-6/JAK2/STAT3 axis, LDOC1 may play different roles during different stages of lung cancer." (PMID 30634502, 2019). "Results from qMSP indicated that the CpG-rich regions of LDOC1 promoter, mLDOC1-2 and mLDOC1-4, were apparently methylated in lung cancer cell lines A549, H1355, and H1299, with additional methylated mLDOC1-1 presented in H1299, which show LDOC1 as completely silenced." (PMID 30634502, 2019). "In Bhattacharjee's study, LDOC1 expression markedly downregulated in all of the 6 small-cell lung carcinoma (SCLC), the lung cancer type most strongly associated with cigarette exposure, compared to the normal lung tissues (without information of smoke status, n = 17)." (PMID 26317789, 2015). "Therefore, STAT3 activation induced by LDOC1 silencing may be associated with genetic abnormalities of EGFR and ALK and may exert a synergistic effect in lung cancer; this topic may be worth exploring in the future." (PMID 30634502, 2019). "According to the tobacco-exposure sensitivity and in vitro anti-tumorigenic activity, we proposed that, in addition to oral cancer and lung cancer, LDOC1 may function as a tumor suppressor gene and is downregulated in several human cancers associated with smoking." (PMID 26317789, 2015). "This study highlighted that LDOC1 acts as a novel native negative regulator of JAK2 and STAT3 in lung cancer." (PMID 30634502, 2019). "The present study is the first to illustrate that LDOC1 functions as a bridge between tobacco smoke exposure and IL-6/JAK2/STAT3 activation in lung cancer." (PMID 30634502, 2019).
lung carcinoma (continued). "LDOC1 interacts with Ligand-of-Numb protein X1 (LNX1), an E3 ligase, to induce Janus kinase 2 (JAK2) ubiquitination and degradation, which negatively regulates STAT3 activation and IL-6 secretion in lung cancer cells." (PMID 39682774, 2024). "However, the effect of LDOC1 in lung cancers has not been elucidated." (PMID 30634502, 2019).
gastric cancer (4 papers, 2014 to 2020). A primary or metastatic malignant neoplasm involving the stomach. "LDOC1 was first identified as a gene encoding a leucine zipper protein whose expression was decreased in a series of pancreatic and gastric cancer cell lines." (PMID 26637328, 2015). "Leucine zipper downregulated in cancer 1 (LDOC1) was originally identified using differential RNA display to be downregulated in a series of pancreatic and gastric cancer cell lines." (PMID 26637328, 2015). "LDOC1 was previously identified as a differentially expressed gene in certain human cancers; for example, the gene was differentially expressed in pancreatic and gastric cancer cell lines." (PMID 26637328, 2015). "LDOC1 has been reported to be downregulated in pancreatic and gastric cancer cells." (PMID 24586797, 2014).
oral squamous cell carcinoma (4 papers, 2019 to 2024). "In oral squamous cell carcinoma, LDOC1 inhibited microbe-induced IL-1β production by regulating the phosphoinositide 3-kinases (PI3K)/protein kinase B (Akt)/phospho-glycogen synthase kinase 3 beta (pGSK-3β) signaling pathway." (PMID 39682774, 2024). "In the present study, we determined salivary LDOC1 expression levels in oral squamous cell carcinoma (OSCC) subjects to investigate the potential of salivary LDOC1 as a biomarker of oral cancer." (PMID 30993049, 2019). "We determined the expression levels of LDOC1 in the saliva of oral squamous cell carcinoma (OSCC) subjects, and investigated its correlation with various clinicopathological characteristics." (PMID 30993049, 2019). "A recent study comparing saliva samples from patients with oral squamous cell carcinoma revealed a gender-specific difference in LDOC1 expression: while LDOC1 expression levels were low in males, LDOC1 expression levels were considerably higher in female patients." (PMID 33291445, 2020).
ovarian carcinoma (3 papers, 2019 to 2022). A malignant neoplasm originating from the surface ovarian epithelium. "Downregulation of LDOC1 was shown in various tissue samples like colorectal cancer, papillary thyroid cancer and cervical and ovarian cancer." (PMID 33291445, 2020). "For instance, down-regulation of LDOC1 due to epigenetic silencing by promoter hypermethylation is widely known in oral, cervical and ovarian cancers." (PMID 31889905, 2019). "In ovarian cancer, LDOC1 is downregulated through promoter methylation and may act as an early marker." (PMID 35957693, 2022). "In addition to tumor identities such as pancreatic, esophageal and colorectal cancer, a downregulation of LDOC1 has also been found in cervical and ovarian cancer." (PMID 33291445, 2020).
papillary thyroid carcinoma (3 papers, 2015 to 2022). "Numerous studies demonstrated that the LDOC1 gene inhibits ligand-induced NF-κB activity in oral squamous cell carcinoma, papillary thyroid carcinoma, and pancreatic cancer cells." (PMID 35957693, 2022). "Remarkably, it has been revealed that papillary thyroid carcinoma tissues exhibit decreased expression of LDOC1 versus the normal thyroid tissues." (PMID 31842997, 2019).
glioblastoma (2 papers, 2010 to 2019). The most malignant astrocytic tumor (WHO grade IV). "LDOC1 is a known miRNA target and has been previously validated as a target of hsa-miR-155 in glioblastoma." (PMID 31889905, 2019). "We inferred that hsa-mir-155 could induce cancer through regulation of apoptosis gene LDOC1 in glioblastomas." (PMID 21143783, 2010).
lung adenocarcinoma (2 papers, 2019 to 2026). A carcinoma that arises from the lung and is characterized by the presence of malignant glandular epithelial cells. "Loss and gain of LDOC1 functions enhanced and attenuated aggressive phenotypes in lung adenocarcinoma A549 and non–small cell lung carcinoma H1299 cell lines, respectively." (PMID 30634502, 2019).
oral cancer (2 papers, 2015 to 2019). "Low LDOC1 expression levels have been correlated with oral cancer caused by exposure to cigarette smoke." (PMID 30993049, 2019). "The X-linked tumor suppressor gene LDOC1 is reported to be involved in oral cancer." (PMID 30993049, 2019). "Future in vitro and in vivo studies are required to determine how gender-specific LDOC1 expression contributes to oral cancer." (PMID 30993049, 2019). "The aim of the present study was to investigate the potential of salivary LDOC1 as a biomarker of oral cancer." (PMID 30993049, 2019). "The role of LDOC1 in oral cancer formation requires further clarification." (PMID 30993049, 2019). "There have been few investigations into the effect of LDOC1 expression in oral cancer." (PMID 30993049, 2019).
vulvar carcinoma (2 papers, 2020 to 2022). "Vulvar carcinoma sections of 157 patients were immunohistochemically stained and examined regarding LDOC1 expression by using the immunoreactive score (IRS)." (PMID 33291445, 2020). "Since the signaling pathway around NF-κB plays a crucial role in vulvar carcinomas and is regulated by LDOC1, the effect of a possible inhibitor C-DIM 12 on the vulvar carcinoma cell lines A431 and SW 954 was investigated in the present study." (PMID 33291445, 2020). "Regarding the nuclear expression of LDOC1, 11% of the vulvar carcinoma tissue sections showed a weak color reaction (IRS 1–2), 33.1% showed a moderate color reaction (IRS 3, 4, 6), and 3.1% of the specimens showed a strong color reaction (IRS 8)." (PMID 33291445, 2020). "In the present study, we investigated the expression of LDOC1 in vulvar cancer tissue and infiltrating immune cells and a further regulation of LDOC1 in vitro." (PMID 33291445, 2020). "Baseline expression levels of LDOC1 in the vulvar cancer cell lines A431 and SW 954 was analyzed by real-time PCR." (PMID 33291445, 2020). "Since no information about the expression and involvement of LDOC1 in vulvar cancer exists to date, we analyzed the expression of LDOC1 in tissue samples and vulvar cancer cell lines." (PMID 33291445, 2020). "The LDOC1 staining process in the cytoplasm resulted in a weak color reaction in 27.6% of the vulvar carcinoma tissue sections (IRS 1–2), 52.7% showed a moderate color reaction (IRS 3, 4, 6), and 9.5% of the specimens showed a strong color reaction (IRS 8, 12)." (PMID 33291445, 2020). "Additionally, a possible regulation of LDOC1 in vulvar cancer cell lines via the NF-κB signaling pathway was analyzed." (PMID 33291445, 2020). "Due to the lack of information about LDOC1 and its exact functionality, this study focuses on the expression of LDOC1 in vulvar carcinoma cells and its surrounding immune cells as well as its correlation to clinicopathological characteristics and prognosis." (PMID 33291445, 2020). "LDOC1 was identified as a negative prognostic marker in vulvar cancer by immunohistochemical staining, showing a negative association with patients’ disease-free survival as well as overall survival." (PMID 33291445, 2020). "Since macrophages can have a negative influence on the tumor, it seems plausible that they express LDOC1, as it was identified as a negative prognostic marker for vulvar cancer in this study." (PMID 33291445, 2020). "Our group showed negative prognosticators in vulvar cancer patients, such as LDOC1 or combined expression of COX-2 and PPARγ in cytoplasm of vulvar cancer tissue." (PMID 35563052, 2022).
brain tumor (1 paper, 2024). "In addition, because the EGFR–AXL complex has been detected in brain tumor cells, and EGFR can form heterodimers with HER2 and HER3, LDOC1 may also affect cellular transport, including internalization and PM recycling of these EGFR-interacting partners." (PMID 38338651, 2024).
chronic periodontitis (1 paper, 2025). A chronic inflammatory process that affects the tissues that surround and support the teeth. "Downregulation of tumor suppressor genes including IRF1, LDOC1, and FOXO3 was also evident in tissues from patients with chronic periodontitis." (PMID 40924302, 2025).
ependymoma (1 paper, 2022). A WHO grade II, slow growing tumor of children and young adults, usually located intraventricularly. "Consistent with the accessibility of NFκB binding motifs, the promoter of LDOC1, a negative regulator of NFκB in ependymoma and other cancers, was only accessible in neuroepithelial-like tumor cells." (PMID 35803925, 2022).
epilepsy (1 paper, 2023). A brain disorder characterized by episodes of abnormally increased neuronal discharge resulting in transient episodes of sensory or motor neurological dysfunction, or psychic dysfunction. "There were 8 DEGs (Ldoc1, Nefh, Parm1, Ptpro, Pvalb, Spp1, Synpr, Vamp1) shared by the schizophrenia and epilepsy gene sets, suggesting a common molecular basis between the two disorders." (PMID 37545878, 2023).
esophageal cancer (1 paper, 2015). A primary or metastatic malignant neoplasm involving the esophagus. "LDOC1 downregulation and differential expression have also been characterized in tissue samples of esophageal cancer and various types of leukemia, which suggests that LDOC1 likely functions as a tumor suppressor." (PMID 26637328, 2015).
Ewing sarcoma (1 paper, 2012). A small round cell tumor that lacks morphologic, immunohistochemical, and electron microscopic evidence of neuroectodermal differentiation. "The expression of the selected target genes in Ewing’s sarcoma (CAV1, NR0B1, IGFBP3 and TGFBR2), together with the expression of HIST1H4L, KCNN2, ECRG4 and LDOC1, was then validated in an independent series of PCa with and without ETS gene fusions, as well as in a series of ESFT and ARMS." (PMID 23185447, 2012).
hepatocellular carcinoma (1 paper, 2022). A malignant tumor that arises from hepatocytes. "However, the expression and function of LDOC1 in hepatocellular carcinoma (HCC) remain unknown." (PMID 35957693, 2022).
hereditary prostate cancer (1 paper, 2019). "Although LDOC1 downregulation was observed in many human malignancies, no genetic mutation of LDOC1 has thus far been identified in tumors, except in hereditary prostate cancer." (PMID 30634502, 2019).
liver cancer (1 paper, 2022). An epithelial or non-epithelial malignant neoplasm that arises from the liver. "Thus, the Western blot was used to explore the potential molecular effects of LDOC1 on liver cancer in this study." (PMID 35957693, 2022). "However, to date, no information about the expression and function of LDOC1 in liver cancer exists." (PMID 35957693, 2022).
oral premalignant lesions (1 paper, 2015). "The result demonstrated LDOC1 expression was mainly located in the cytoplasm and 76.5% (13/17) normal oral tissues showed LDOC1 high expression, compared to 53.3% (8/15) oral premalignant lesions (OPML, including hyperplasia squamous epithelium and benign tumors) showing no or low LDOC1 expression." (PMID 26317789, 2015).
prostate tumor (1 paper, 2012). "No methylation was detected at the TGFBR2 and LDOC1 promoters in prostate tumor samples." (PMID 23185447, 2012).